ICAM1 (intercellular adhesion molecule 1)
Diseases named in the same sentence as ICAM1 in open-access papers (continued):
Sharing a sentence is not in itself a finding about the gene and the disease.
tumor (continued). "In a preliminary study we reported that soluble ICAM-1 increases by two-fold in the supernatant of tumor-activated HSE cells and that, in turn, soluble ICAM-1 increases CT26 cell secretion of VEGF." (PMID 18844982, 2008). "The combination of B7.1, ICAM-1 and LFA-3 (TRICOM) appears to be particularly useful for both in vitro stimulation of T cells and for induction of tumor rejection in vivo." (PMID 18039393, 2007). "In several tumour cell lines, TNF-α induced the expression of several different adhesive molecules including several integrin subunits, ICAM-1 and VCAM-1." (PMID 15841081, 2005). "Docetaxel increased the expression of the adhesion molecules LFA-3, ICAM-1, CD44s+v6 isoforms, CD15, CD13 and VLA-4/5/6 on the tumour cells." (PMID 12085250, 2002). "The expression of the intercellular adhesion molecule-1 (ICAM-1, CD54) seems to have an influence on the metastatic behaviour of tumour cells via immunological mechanisms." (PMID 9514061, 1998). "Notably, the MSI/ICAM1 pathway is highly expressed in GBM cells, playing an important role in oncogenic resistance, particularly in enhancing tumor invasion, suggesting that MSI1/ICAM1 represents a promising therapeutic target for GBM." (PMID 40838069, 2025). "Importantly, the percentage of CD8+ and CD4+ T cells in the ICAM‐1–Dxd plus B7‐H3‐CD3 group was markedly greater than that in the other groups, demonstrating immune cell infiltration in tumor tissues." (PMID 39996528, 2025). "In addition, the expression of metastasis-related markers matrix metallopeptidase 2 (MMP2), MMP9, and intercellular cell adhesion molecule-1 (ICAM1) was decreased, suggesting that METTL3 overexpression suppressed transcription of key tumor metastasis genes." (PMID 41208889, 2025). "A recent study confirmed these findings, demonstrating CD29-negative tumor cells in 67% and ICAM-1-negative tumor cells in 95% of IVLBCL cases, in contrast to DLBCL, where these molecules are typically expressed." (PMID 40723240, 2025). "Moreover, RT upregulates adhesion molecules like intracellular adhesion molecule 1 (ICAM-1) and vascular cell adhesion molecule 1 (VCAM-1) on tumor blood vessels, facilitating CAR-T cell infiltration into the tumor microenvironment." (PMID 39881333, 2025). "Inefficient trafficking results from abnormal tumor vasculature, a lack of adhesion molecules (e.g., intercellular adhesion molecule-1 [ICAM-1]) and chemokines, and ‘anergic’ vessels that are unresponsive to inflammatory signals." (PMID 40821802, 2025). "Additionally, RT can normalise tumour blood vessels by increasing the expression of adhesion molecules ICAM-1 and VCAM-1, which facilitates CAR-T-cell migration into the tumour." (PMID 40906384, 2025). "It appears that upon initial antigen encounter, effector-polarized CAR-T cells, particularly those with CD28 co-stimulation, produce substantial IFNγ, which enhances ICAM-1 expression on tumor cells and facilitates subsequent CAR-T cell infiltration into tumor tissue." (PMID 41154636, 2025). "In tumor samples, CXCL-12, VCAM-1, and ICAM-1 levels negatively correlated with surgery duration." (PMID 40652770, 2025). "Notably, MES-like tumor cells and GPNMB+ MDMs were predominantly localized to peri-necrotic regions, whereas ICAM1+ MDMs, COL6A3+ TAFs, and endothelial cells were enriched in peri-vascular areas." (PMID 41174767, 2025). "Increased Icam1 mRNA levels (an anti-tumor N1 phenotype marker) were also observed, although no corresponding neutrophil population (ICAM+) was detected by flow cytometry." (PMID 40867260, 2025). "Notably, tumor cell membranes also highly express CD44 receptors, integrin receptors, ICAM-1, and VCAM-1." (PMID 40528159, 2025). "In the RLS40 model, the neutrophil phenotype was associated with the tumor growth rate, where, in aggressively progressed tumors (RLS40High), CCL17 was expressed, while, in mice with controlled tumor growth (RLS40Low), anti-tumor markers were expressed (FAS, ICAM-1, PD-L1)." (PMID 40867260, 2025).
tumor (continued). "ICAM1 binds to ligands like LFA-1 and MAC-1, which play roles in inflammation and tumor metastasis." (PMID 40352921, 2025). "Clinical monitoring of post-RT tumor ICAM-1 expression may enhance PET interpretation and aid in distinguishing pseudoprogression from true tumor progression." (PMID 41416923, 2025). "Because metastatic cells, unlike leukocytes, do not express β2-integrins, ligands required to interact with ICAM-1, the adhesion of tumor cells occurs by bridging by immune cells." (PMID 39780275, 2025). "Furthermore, we found that MES-like tumor cells and GPNMB+MDMs co-localize in the PAN region, whereas COL6A3+TAFs and ICAM1+MDMs are distributed adjacent to MVP niches for the first time, revealing the unique spatial ecological niches in GBM patients." (PMID 41174767, 2025). "This was again opposite to that PAK4KO promoted ICAM-1 and VCAM-1 expression and vascular normalisation in a syngeneic mouse model, suggesting the PAK4KO-stimulated anti-tumour immunity may contribute to its effect on vascular normalisation." (PMID 41228228, 2025). "For example, tumor‐associated ECs frequently display reduced expression of vascular adhesion molecules (such as ICAM‐1 and VCAM‐1), which are required for the homing and trafficking of immune cells and act as a barrier to prevent immune cells from entering the tumor interior." (PMID 41346571, 2025). "ICAM-1 and VCAM-1 are key adhesion molecules that mediate leukocyte adhesion and migration across the endothelium, thereby regulating the immune responses, inflammation, and tumour progression." (PMID 41294859, 2025). "Further, targeting of SLAMF7 on CD8+ T cells could serve as a mean to regulate the formation of ICAM-1-LFA-1 dependent CTL populations within the tumor tissue, and by enrichment of tumor-specific CD8+ T cells, SLAMF7 signals could improve the tumor control." (PMID 39390117, 2025). "In addition, compared with the other groups, the ICAM‐1–Dxd plus B7‐H3‐CD3 group presented a significantly reduced number of Ki67‐positive cells, leading to substantial and sustained inhibition of tumor growth." (PMID 39996528, 2025). "N1-type neutrophils, characterized by their anti-tumor phenotype, exhibit hypersegmented nuclei and high expression levels of factors such as tumor necrosis factor-α (TNF-α), intercellular adhesion molecule-1 (ICAM-1), vascular cell adhesion molecule-1 (VCAM-1), and CCL3." (PMID 40282474, 2025). "Second, although ICAM1 is significantly overexpressed in ATC and other aggressive cancers, its physiological expression in normal organs raises concerns about potential “on‐target, off‐tumor” toxicity." (PMID 40539828, 2025). "Furthermore, IL-6 increases the expression of adhesion molecules, such as ICAM-1, VCAM-1 and E-selectin on endothelial cells, as well as L-selectin on lymphocytes, which results in increased transmigration of leukocytes into the tumor area." (PMID 41009634, 2025). "Consequently, upon disruption of the LFA-1/ICAM-1 and VLA-4/VCAM-1 axes, NK cells lose their intravascular localization, compromising surveillance of metastasizing tumor cells." (PMID 41145419, 2025). "However, under gemcitabine treatment, PAK4KO significantly upregulated both ICAM-1 and VCAM-1 compared with WT tumours, suggesting an activation of these molecules following the gemcitabine treatment." (PMID 41294859, 2025). "It influences the migration and infiltration of immune cells into tumor tissues by modulating chemokines (e.g., CXCL12) and adhesion molecules (e.g., ICAM-1), and affects immune cell activation and anti-tumor responses by regulating the expression and function of immune cell surface receptors." (PMID 40181983, 2025). "Moreover, radiotherapy promotes CD8+-T-lymphocyte mediated tumour cell killing via ICAM-1 and MIC A/B so that inflammatory remodelling of the microenvironment leads to increased tumour cell death (reviewed by Donlon)." (PMID 41464778, 2025).
tumor (continued). "Moreover, ABO blood group status is associated with circulating inflammatory markers suchas intercellular adhesion molecule-1 (ICAM-1) and tumor necrosis factor-alpha (TNF-α), which are involved in the tumor microenvironment." (PMID 41466714, 2025). "Specifically, tumor-derived PGRN promoted the polarization of TAMs to M2 macrophages, and then, PGRN-treated TAMs inhibited proliferation and activation of CD8 + T cells via ICAM-1-mediated interaction with CD8+T cells in BCa tumor microenvironment." (PMID 38554213, 2024). "In contrast, the evaluation of GCSCs from non-tumor tissue samples showed that the cell surface marker ICAM1 was absent." (PMID 39201551, 2024). "Furthermore, fibrinogen can bind directly to the intercellular adhesion molecule-1 (ICAM-1) on endothelial cells, enhancing tumor cell adhesion, proliferation, and migration." (PMID 38978733, 2024). "One can hypothesize that as HA CAR-T cells release higher levels of IFN-γ upon co-culture with tumor cells as compared to LA CAR-T cells, they can induce increased upregulation of ICAM-1 and therefore, increased resistance to PD-L1." (PMID 38670972, 2024). "Finally, we developed a monoclonal antibody against ICAM-1–FGG binding motif, which blocks ICAM-1‒FGG interaction and effectively suppresses NSCLC cell survival in vitro and tumor growth in vivo." (PMID 39168965, 2024). "Compared with injection of phosphate-buffered saline (PBS) control, injection of the anti-ICAM-1 antibody alone did not affect tumor growth and exerted limited effects on the tumor-infiltrating immune cell population." (PMID 38169608, 2024). "Besides, tumor endothelial cells express soluble ICAM-5, which functions as an inhibitor of LFA-1, counteracting the pro-inflammatory effects of ICAM-1 by reducing the activation of T lymphocytes." (PMID 39076974, 2024). "In vivo experiments revealed co-expression of ICAM1 and MMP9 on tumor cells." (PMID 38907234, 2024). "ICAM-1 and RHAMM were expressed in the majority of tumor cells." (PMID 38600583, 2024). "In addition, we observed a significantly higher level of ICAM-1, which has been suggested as an important mediator of CD14+ monocyte adhesion in tumor microenvironment." (PMID 39201392, 2024). "Moreover, we discovered alterations in the expression of immune-regulatory genes in cells devoid of C22orf46 expression, enhancing tumor visibility to the immune system such as CXCL11, ICAM-1, or IL-10." (PMID 38228372, 2024). "ICAM-1 has been reported to be rapidly induced after the onset of severe hypoxia, supporting the findings from this study whereby ICAM-1 elicited intensive expression within centralized tumor cells bounded by circular pseudo-palisades." (PMID 38258133, 2024). "However, CD274/PD-L1, CD54/ICAM-1, HLA-DR, MHC class I, CD95/FasR, and CD270/HVEM are regulated in various tumour types." (PMID 38748263, 2024). "Through an in vitro co-culture system, we found that neutrophils exhibit greater adhesion to TNBC cells than to non-TNBC cells, suggesting that ICAM1 plays a role in tumor cell interactions with neutrophils." (PMID 38907234, 2024). "Although not directly linked to fluid shear stress, tumor-associated endothelial cells down-regulate genes related to immune extravasation, such as ICAM-1 and VCAM-1, in many cancers, further contributing to a less permissive environment for NK cell extravasation to the tumor tissue." (PMID 38671750, 2024). "ICAM1 thus acts as an immune trigger, with an opposing function to immune checkpoint proteins, and it is possible that a therapeutic enhancement of ICAM1/LFA-1 interaction between AML and T cells could enable T cell activation and tumor control." (PMID 38724673, 2024). "Finally, two further downregulated genes were ICAM1, coding for CD54 protein driving tumor growth and ARAF, whose overexpression in HCC initiation and progression has been previously demonstrated." (PMID 38834875, 2024).
tumor (continued). "Of note, GCSCs without ICAM1 exhibited decreased migration in xenotransplanted zebrafish, but they showed a more aggressive cell behavior, resulting in a tumoral mass in situ that was able to disrupt the structures in the yolk sac and cause a severe phenotype." (PMID 39201551, 2024). "VS-6063 induced an increased proportion of ICAM-1+ cells among the total tumor-infiltrating cells and CD45+ cells without impacting CD45- cells." (PMID 38169608, 2024). "We found that CXCL8 increased ICAM1 expression in MLKL-overexpressing tumour cells that were co-cultured with macrophages, while no changes were observed when MLKL-overexpressing tumour cells were cultured alone." (PMID 39025845, 2024). "In addition, ICAM-1 promotes TNBC cells to secrete suPAR, which functions as a neutrophil chemoattractant to facilitate tumor cell and neutrophil binding." (PMID 37345070, 2023). "In a breakthrough animal experiment, it was found that ICAM-1 CAR-T cells that target intercellular adhesion molecule-1 can mediate strong and lasting anti-tumor activity, leading to tumor eradication and a significant increase in the long-term survival of ATC xenograft mouse models." (PMID 37007127, 2023). "Truncation of cytoplasmic tail of ICAM-1 (ICAM1-ΔC) did not alter rescue of tumor cell killing compared to full-length ICAM1." (PMID 37732732, 2023). "Neuropilin-1 had a very similar pattern to that of ICAM-1, where it was expressed by non-proliferating rather than proliferating tumor cells and by (cytotoxic) neutrophils in both the proximal and border regions." (PMID 36672243, 2023). "In vivo imaging results showed that, in comparison with non-targeted IgG-Cy5.5, ICAM1-Cy5.5 and ICAM1-MMAE-Cy5.5 had significantly higher accumulation at CCA tumor sites." (PMID 37717087, 2023). "Additionally, radiation therapy can increase the expression of adhesion molecules like intercellular adhesion molecule-1 (ICAM-1) and vascular cell adhesion molecule-1 (VCAM-1) on tumor endothelial cells." (PMID 38162672, 2023). "Furthermore, ICAM-1 directly regulates macrophage polarization affecting CTL killing of tumor cells." (PMID 37732732, 2023). "Instead, ICB efficacy was robustly identified through the in situ hotspot detection of galectin-3-positive non-proliferating tumor zones enriched in cell death and infiltrated by anti-tumor cytotoxic neutrophils positive for ICAM-1 and neuropilin-1." (PMID 36672243, 2023). "In non-inflamed TME and highly angiogenic tumor state, bFGF/VEGF activities influence ECs toward decreased expression of endothelial adhesion molecules (EAMs), including E-selectin, ICAM1, and VCAM1, thus hindering leukocyte homing, extravasation, and infiltration into tumor tissue." (PMID 37727791, 2023). "ICAM‐1 mAb and siRNA result in a downregulation of CX3CL1‐induced tumour metastasis in OSCC cells." (PMID 37082943, 2023). "Induction of ICAM-1, VCAM-1, and E-selectin in ECs has been shown to promote tumor cell adhesion." (PMID 37124539, 2023). "Notably, Gene Set Enrichment Analysis (GSEA) revealed that type I interferon signaling pathway was the most enriched one in PDX tumor tissues treated with ICAM1-DXd in comparison with PBS, ICAM1 mAb, and ICAM1-MMAE." (PMID 37717087, 2023). "TNBC cells with low ICAM1 expression subjected to co-culture with THP-1 cells underwent treatment with phorbol 12-myristate 13-acetate (PMA) and CD8 T cells to study the alterations in ICAM1 expression in the tumor microenvironment." (PMID 37671167, 2023). "Prevention of spheroid formation by macrophage depletion or anti‐ICAM‐1 antibodies, or pharmacological blockade of EGFR, significantly delayed tumor growth, supporting that peritoneal macrophages are critical for ovarian cancer metastatic progression by driving spheroid formation." (PMID 36658699, 2023). "Also, phosphorylated STAT3 leads to the upregulation and overproduction of intercellular adhesion molecule 1 (ICAM 1), contributing to tumor migration and invasion." (PMID 38067351, 2023).
tumor (continued). "Liver was the major non-tumor accumulation site of ICAM1-Cy5.5 and ICAM1-MMAE-Cy5.5 as well as non-targeted IgG-Cy5.5." (PMID 37717087, 2023). "To investigate whether tumor cells accumulated on the choroid plexus, we determined the expression of the ICAM2 and ICAM1 proteins." (PMID 37620448, 2023). "ICAM1, PLCG1, PLCG2 and other genes in the pathway are also related to tumor migration." (PMID 37312215, 2023). "On the other hand, VEGF inhibits the adhesion of lymphocytes to endothelial cells through intercellular adhesion molecule-1 (ICAM-1), vascular cell adhesion molecule-1 (VCAM-1), and Fas Ligand (FasL), thereby affecting the infiltration of T cells into the tumor tissue." (PMID 36936932, 2023). "ICAM1 protein was significantly overexpressed in tumor tissues of both iCCA and eCCA, but was absent in the normal human bile duct tissues." (PMID 37717087, 2023). "Interestingly, we found PTHLH derived from tumor cells can target macrophages and regulate the expression of CCL13, PLAU and ICAM1, resulting the phenotype of TAM_c1." (PMID 38044943, 2023). "However, xenograft-derived tumor cells lost Fas, MICB, and ICAM-1 expression, and downmodulated HMGCR, the rate-limiting enzyme of the mevalonate pathway producing pAgs." (PMID 37139603, 2023). "Overexpression of ICAM1 significantly enhanced tumor cell apoptosis, while knockdown of ICAM1 inhibited NK-mediated apoptosis, which indicated that LKB1-induced differences in response to cytotoxic immune cells were dependent on ICAM1." (PMID 36871040, 2023). "ICAM-1 expression correlated with smaller tumor size (p = 0.0443) but not with any other clinical feature or to the patients’ outcome." (PMID 36906717, 2023). "C3 significantly reduced the expression (mRNA level) of inflammatory molecules TNF-α, pro-IL-β, ICAM-1, and VCAM-1 in the tumor tissue, unlike cisplatin, which significantly reduced the expression of pro-IL-β and ICAM-1." (PMID 37569878, 2023). "In addition, ICAM-1 promotes TNBC cells to secrete suPAR, which acts as a chemoattractant for neutrophils and facilitates tumor cell–neutrophil binding." (PMID 37345070, 2023). "The molecular mechanism that has been considered for paclitaxel is that it may increase tumor cell killing by NK cells by enhancing the expression of NKG2D ligands and ICAM-1." (PMID 38057843, 2023). "However, more substantial differences in the expression levels of some genes (ICAM-1, MMP-2, MMP-9, IL-6, and CX-43) were observed, indicating the potential influence of the cancer cell type on secondary tumor progression." (PMID 38001146, 2023). "In the same CCA tumor xenografts, both ICAM1 ADCs exhibited significantly higher potency against CCA tumors than their non-targeting counterparts, suggesting that ICAM1 ADCs can mediate their anti-tumor activity in a tumor-specific manner." (PMID 37717087, 2023). "DC-derived EVs (DC-EVs) contain co-stimulatory molecules, integrin avβ2, intercellular adhesion molecule 1 (ICAM1), and other components involved in cell–cell interactions, which allows DC-EVs to control tumor immune escape by modulating immune stimulation, thereby inhibiting tumor progression." (PMID 35189894, 2022). "Since all major types of hematopoietic CD45+ cells express the ICAM-1 binding LFA-1 and Mac-1 integrins, we next tested if the composition of these cells in the E0771 tumor microenvironment (TME) is affected by the absence of E0771-expressed ICAM-1." (PMID 35911772, 2022). "In another mouse study using tumor-bearing IFN-β −/− mice, TANs displayed protumor behavior, such as reduced expression of ICAM-1 and TNF-α and low cytotoxicity toward tumor cells, implying that IFN-β enhances the polarization of TANs toward the antitumor phenotype." (PMID 35328639, 2022).